MEIS1 (Meis homeobox 1)
Diseases named in the same sentence as MEIS1 in open-access papers (continued):
Sharing a sentence is not in itself a finding about the gene and the disease.
leukemia (continued). "Furthermore, knockdown of Meis2 in our leukemia-derived MN1 cell line results in an approximately 10-fold increase in Meis1 expression (unpaired t-test, n.s.), supporting compensatory expression between these family members." (PMID 28960191, 2017). "Thus, we reveal a differential requirement for the mitochondrial TCA enzyme Fh1 in normal hematopoiesis and Meis1/Hoxa9-driven leukemia propagation." (PMID 28202494, 2017). "In addition, the frequency of c-Kit-positive cells was higher for Hoxa9 and Meis1, and for Hoxa9 and hSYK, compared with Hoxa9 alone, suggesting a more immature phenotype of the developing leukemias." (PMID 28399410, 2017). "Finally, Syk inhibition disrupts the identified regulatory loop, prolonging survival of mice with Hoxa9/Meis1-driven leukemia." (PMID 28399410, 2017). "Evidence for direct binding and regulation of Hlf by Meis1 in leukemia and our work suggests that Meis1 may mediate possible Hlf function in the HSCs." (PMID 26986211, 2016). "To determine whether Prep1 can exert a tumor suppressive role in leukemia induction, we first compared the transformation rate of Prep1i/i and WT fetal liver (FL) cells overexpressing the oncogenic Meis1." (PMID 24809472, 2014). "Flow cytometric immunophenotyping of the leukemias arisen in two sets of mice transplanted with WT or Prep1i/i Meis1-HoxA9-transduced cells, demonstrated that they all were donor-derived as about 90% of the cells expressed GFP and displayed Mac-1 and Gr-1 myeloid cell surface antigens." (PMID 24809472, 2014). "As in leukemia, gene expression studies in lung adenocarcinomas, neuroblastomas, ovarian carcinomas, and nephroblastomas have shown that the expression of Meis1 is elevated in tumor tissues, suggestive of an oncogenic role." (PMID 25013928, 2014). "The message levels of Meis1 transcriptional partners, and other related proteins, that are often co-ordinately upregulated with it in different leukemias, such as Pbx1 and a number of Hox family members was also found to be elevated in the mutants although to different extents." (PMID 23308270, 2013). "MEIS1 is a class A homeodomain protein that acts as a cofactor for homeobox (HOX) proteins, and has been implicated as a critical downstream target of oncogenic fusion proteins in leukemia." (PMID 23442791, 2013). "Importantly, silencing of MEIS1 decreases the proliferation of leukemia-derived cells but increases their survival after etoposide treatment." (PMID 22185299, 2011). "Leukemias characterized by mutations in EZH2, DNMT3A, or ASXL1 or SET-NUP214 or RUNX1-EVI1 fusions also show overexpression of HOXA and MEIS1, and it might hypothetically be reasonable to expect a response to MI; future clinical studies will provide more confirmation about these novel targets." (PMID 39594699, 2024). "However, the CBL0137/panobinostat combination did not induce significant changes in the levels of acetylation or methylation of specific histones associated with KMT2A-r leukemia or in the expression levels of leukemogenic KMT2A target genes such as HOXA9 and MEIS1 before induction of apoptosis." (PMID 35677155, 2022). "Indeed, SYK inhibition prolonged survival of mice with Hoxa9/Meis1-driven leukemia." (PMID 35216478, 2022). "However, knockdown of FABP4 was able to promote survival in HOXA9/MEIS1-driven leukemia model mice." (PMID 36002858, 2022). "It has also been already described that a Meis1 mutated in its HR2 domain could not cooperate with Hoxa9 in colony-forming assays or in in vivo leukemia assays." (PMID 34698191, 2021). "Finally, we performed gene expression studies in MLL-AF9 and MLL-AF6 transformed bone marrow cells and found that genes highly relevant to MLL leukemia (Hoxa5, Hoxa9, Hoxa10, Meis1, and Mef2C) were expressed at much lower levels in the ΔSET Ash1l versus WT Ash1l cells." (PMID 33990599, 2021). "Consequently, HOXA9 and MEIS1 are highly transcribed in MLL fusion-mediated leukemia." (PMID 34310280, 2021).
leukemia (continued). "Therefore, given a possible therapeutic use of MEIS1 in human leukemias, it might be important to analyze better the common interactions with PBX." (PMID 34698191, 2021). "Therefore, it is conceivable that MLL-r leukemia cells with lower expression of the MEIS1/HIF1α pathway are less metabolically flexible in their response to specific mitochondrial stress induced by CCI-006, and thus sensitive to the inhibition of mitochondrial respiration induced by the compound." (PMID 30670779, 2019). "This compound potently inhibits the expression of MLL-fusion target genes HOXA9 and MEIS1, selectively inhibits the proliferation of MLL-rearranged leukemia cells (IC50 = 3.5 nM), and causes complete and sustained regression in a rat xenograft model of MLL-rearranged leukemia." (PMID 31817960, 2019). "The largely overlapping transcriptional consequences of Syk and Meis1 led us to hypothesize that Meis1-transformed leukemias would be more addicted to Syk than to other signaling proteins such as Flt3, which has previously been shown to be dispensable for Meis1-driven leukemias." (PMID 28399410, 2017). "Moreover, the less differentiated and highly proliferative phenotypes of Prep1i/i leukemias may result from the upregulation of Meis1." (PMID 24809472, 2014). "Meis1 was first identified as a major integration site for leukemogenic virus in a murine leukemia model, aberrant activation of Meis1 is related to the genesis of human leukemia, and the defect of Meis1 is intimately related to congenital heart disease as well." (PMID 24639739, 2013). "Importantly, HoxA9 expression alone (but not Meis1 alone) can cause leukemia in mice, although with a much longer latency than HoxA9/Meis1 co-transfected mice, and it is required for MLL-ENL mediated bone marrow transformations." (PMID 24213472, 2012). "KMT2Ar results in fusion proteins that drive leukemia by activating HOX genes and their cofactor Meis1, which are both critical for leukemogenesis." (PMID 41514668, 2026). "In connection with these data, KMT2A::AFF1 fusion protein promotes leukemia progression mainly by activating pro-leukemogenic factors HOXA9 and MEIS1." (PMID 40722046, 2025). "When important oncogenes such as MEIS1 and RUNX2 are overexpressed because of novel enhancer usage, this has clear implications for therapeutic response and patient outcomes in leukemia." (PMID 40729681, 2025). "In these resistant cells, key KMT2A target genes, such as MEIS1 and HOXA, remain suppressed, and although the menin–KMT2A complex is successfully displaced from chromatin by the inhibitors, leukemia persists." (PMID 39682203, 2024). "This cooperation between NPM1c and KMT2A sustains the transcription of key oncogenes like MEIS1 and HOX cluster genes, which are vital for maintaining the stem-cell-like state of leukemia cells." (PMID 39682203, 2024). "A total of 100 TFs with silenced promoters were downregulated relative to AML, including hematopoietic regulators and genes known to be involved in leukemia, such as CEBPA, CEBPD, KLF4, IRF4 or MEIS1." (PMID 38972954, 2024). "The two most important aberrantly expressed genes in KMT2A-rearranged leukemias are HOXA9 and MEIS1 since their upregulation was shown to be crucial for leukemogenesis." (PMID 39834944, 2024). "Pharmacological inhibition of DOT1L in cell line and xenograft models of KMT2A-r leukemia has shown anti-leukemic activity and restores normal HOXA and MEIS1 transcription." (PMID 38174649, 2023). "Despite the absence of a unique transcriptional regulator for SCUBE1, recent research has shown that in MLL-r leukemia, homeobox A9 (HOXA9) and Meis homeobox 1 (MEIS1) act together to upregulate SCUBE1." (PMID 37237303, 2023). "In both cell lines and patient-derived NPM1c leukemia cells menin inhibition removes the menin-KMT2A complex from target gene loci and suppresses expression of especially MEIS1 and its transcriptional target FLT3." (PMID 38174649, 2023).
leukemia (continued). "MI-1481-treated human MLL leukemia cell MV-4-11 was employed to detect the influence of the expression levels of DLX2, MEIS1, and HOXA9, which are all MLL fusion target genes." (PMID 37049787, 2023). "MLL-r leukemia has previously been shown to depend on MEIS1 and co-depend on redundant contributions of PBX proteins in mammalian leukemia models." (PMID 37720104, 2023). "Selected inhibitors were found to suppress expression of MLL target genes HoxA9, Meis1 and Myc and inhibit proliferation of MLL-r leukemia and other AML cells with EC50s as low as 4.7 μM, while they were inactive against solid tumor Hela cells." (PMID 37958457, 2023). "Among the HSC self-renewal genes that are common between the double and triple mutants, Myc1, Zfp521, Meis1, and Zfp532 have been found to be functional not only in HSC self-renewal and differentiation, but also in leukemia progression and maintenance." (PMID 36073548, 2022). "We also observed the aberrant overexpression of MEIS1 and HOXA9, members of the same family as MEIS3, that is highly effective in transforming hematopoietic progenitors and driving mice toward a lethal leukemia." (PMID 36002858, 2022). "DOT1L methyltransferase inhibitors increase differentiation of MLLr leukemia cells and decrease proliferation, global H3K79me, and expression of HOXA9 and MEIS1." (PMID 35712672, 2022). "Other studies showed that PBX1, HOXA, and MEIS1 bind to the MYB gene, activating and dysregulating it in leukemia." (PMID 35743243, 2022). "HOXA9/MEIS1 are essential co-factors for KMT2A-driven leukemogenesis, making it possible that a CDX2-HOXA9/MEIS1 axis exerts a similar leukemia promoting role in UBTF::ATXN7L3 ALL." (PMID 35397658, 2022). "How compound 1-mediated ENL degradation changes expression of HoxA9, Meis1 and Myc, three characteristic genes in MLL1-r leukemia, was examined." (PMID 35395864, 2022). "In MLL-fused leukemia cells, the RELA-p50 complex binds to MLL1 and induces trimethylation of histone H3K4 residues in the promoter regions of HOXA9 and MEIS1." (PMID 36362853, 2022). "Selective drugs developed to restrain the proliferation of MLL-r leukemia cells through inhibiting DOT1L due to the ability of inducing the hyperexpression of HOXA9 and MEIS1." (PMID 36376832, 2022). "DOT1L, however, is dispensable for BCR-ABL, E2A-HLF, E2A-PBX2 leukemias, and leukemia generated by ectopic retroviral overexpression of HOXA9/MEIS1." (PMID 35712672, 2022). "DOT1L has been found to be required for expression of MLL1-target genes such as HoxA9 and Meis1 and therefore a drug target for MLL1-r leukemia." (PMID 33823889, 2021). "On the other hand, Bcl2 deletion delayed the onset of leukemia induced by MLL-AF10 and the HOXA9/MEIS1 combination in vivo." (PMID 34310280, 2021). "We also show that stimulation of leukemia cells with FGF2 increases nuclear level of FGFR2 in its phosphorylated form, as well as HOXA9 and MEIS1 expression." (PMID 33924850, 2021). "DOT1L methyltransferase activity is critical to MLL-r leukemia and is recruited on DNA where it induces hyperexpression of HOXA9 and MEIS1." (PMID 34698191, 2021). "The HoxB5, HoxA9, and Meis1 oncogenes were inserted into ML-23 leukemic cell line DNA, which suggests that they were involved in inducing AML-like leukemia in our model." (PMID 33602907, 2021). "The HMT DOT1L plays a key role in initiation and maintenance of MLL-rearranged leukemia, because of its role in H3K79 methylation and subsequent upregulation of Meis1 and HOXA." (PMID 34012921, 2021). "Transcription factor MEIS1 is an HSC marker, and its expression level declines with cell differentiation; it is known to promote expression of stem cell markers in leukemias." (PMID 33919312, 2021).
leukemia (continued). "Mechanistically, these anti-leukemia effects of I-BET151 are likely due to its suppression of ZM-activated pro-leukemic genes, including Hoxa7, Hoxa9, Meis1, Myc and Myb." (PMID 33594072, 2021). "Several generations of improved inhibitors have demonstrated specific inhibition of leukemia cell growth in vitro, induction of differentiation as well as downregulation of both HOXA9 and MEIS1 expression." (PMID 33542482, 2021). "Knowing that DOT1L primarily drives Hoxa9 and Meis1 expression for the initiation and maintenance of MLL-AF9 leukemia, we expected that with decreased H3K79me2, we would see a profound decrease in expression of MLL target genes." (PMID 33562706, 2021). "As expected, the group of genes we identified as the most frequent KMT2A fusion targets across our collection of samples included several genes that are known to be required for KMT2Ar leukemia, including HOXA9, MEIS1, MEF2C, MBNL1 and JMJD1C25–29." (PMID 34663924, 2021). "MN1-driven leukemia is characterized by a CMP-like gene expression program that includes high expression of Hoxa9 and Meis1, known target genes of Kmt2a-fusion proteins but also of wild type Kmt2a." (PMID 33542482, 2021). "Other studies have supported a role of Meis1 and HoxA9 in cooperation with IDH1 or IDH2 mutant to drive leukemia development in mouse models." (PMID 32859092, 2020). "LAMP5-AS1 knockdown significantly reduced the global H3K79me2/me3 levels in MLL leukemia cells, resulting in significantly decreased expression of the stem gene HOXA cluster and MEIS1 and decreased cell self-renewal capacity." (PMID 32552847, 2020). "Using a knock-in model of mouse leukemia (MLL-AF9), it has been demonstrated that MEIS1 is necessary for maintaining an ESC-like gene signature." (PMID 32819319, 2020). "MEIS1-PBX and HOX-PBX heterodimer complexes have been shown to occupy promoter regions of leukemia-related genes." (PMID 33402862, 2020). "We demonstrated that LAMP5-AS1 knockdown triggered a decreased H3K79 methylation state on the locus of the HOXA genes and MEIS1, which remarkably inhibited MLL leukemia cell self-renewal and promoted differentiation." (PMID 32552847, 2020). "MEIS1 has historically been described as a HOX cofactor, collaborating with HOX genes in the development of leukemia." (PMID 30670779, 2019). "We showed that the group of sensitive MLL-r leukemia cells is characterized by a particular gene expression profile (low HOXA9, MEIS1, and CMYC mRNA levels) and low levels of MEIS1/HIF1α protein expression." (PMID 30670779, 2019). "This translocation defines a leukemia subtype closely related to MLL-r leukemia, and is driven by shared mechanisms such as upregulation of the leukemogenic HOXA9/MEIS1 pathway." (PMID 30670779, 2019). "CCI-006 treatment increased the levels of CHOP mRNA and phosphorylated JNK (p-JNK) and diminished the levels of HOXA9, MEIS1, and CMYC, important leukemogenic drivers and survival factors for MLL-r leukemia in sensitive MLL-r leukemia cells." (PMID 30670779, 2019). "Accordingly, leukemic cells carrying the BCR–ABL, MLL–AF9 fusion proteins, and co-expressing HoxA9 and Meis1 were all affected by the inactivation of Pml in MSCs, thus suggesting the possibility that the same therapeutic intervention could be beneficial in multiple leukemia sub-types." (PMID 29302031, 2018). "MLL-r leukemia cells express a subset of genes including HOXA9 and MEIS1 whose expression is normally confined to immature hematopoietic cells such as hematopoietic stem cells (HSCs) (hereafter we refer to as HSC program genes)." (PMID 30693017, 2018). "When miR-196b was over-expressed in leukaemia cells, it represses the function of FAS and at the same time promotes cell proliferation and inhibits apoptosis via increases expression of HOXA9/MEIS1." (PMID 28458781, 2017). "Although Meis1 alone is unable to promote self-renewal, it plays a role in establishing LSC potential in MLL-rearranged leukemias." (PMID 28399410, 2017).
leukemia (continued). "Consistent with DOT1L loss-of-function studies, these DOT1Li also selectively inhibited expression of MLL-fusion target genes such as HOXA9 and MEIS1 and selectively killed MLL-rearranged leukemia cells and xenografted tumors." (PMID 29075615, 2017). "The fact that many Nup98 fusion-mediated leukemias appear to be triggered by activation of the HOXA and HOXB loci and Meis1 strongly suggests that the recruitment of the N-terminal portion of Nup98 fusions (through Nup98 itself) is a critical step." (PMID 29269482, 2017). "In MLL-r leukemias, HOXA9 and its dimerization partner MEIS1 are the most well-characterized direct targets, which in turn can replace MLL-fusion proteins in overexpression experiments." (PMID 28974232, 2017). "Among these MLL targets genes, such as HOXA9 and MEIS1, it is well established the crucial role played in MLL-induced leukemia, however many other of the genes strongly deregulated by MLL fusion proteins remain poorly characterized." (PMID 28412727, 2017). "For instance, dysregulation of HOX gene family members play a dominant role in mechanism of leukemic transformation and those co-factor MEIS1 quantitatively regulates the differentiation, cycling activity and self-renewal of MLL leukemia cell." (PMID 29033978, 2017). "CCI-007 altered the characteristic MLL-r gene expression signature in sensitive cells with downregulation of the expression of HOXA9, MEIS1, CMYC and BCL2, important drivers in MLL-r leukemia, within a few hours of treatment." (PMID 27317766, 2016). "MLL-r leukemia is characterised by deregulated gene expression that reportedly entails increased expression levels of HOXA9, MEIS1, CMYC and BCL2, which have been suggested to play important roles in MLL-r leukemia cell survival." (PMID 27317766, 2016). "In leukemias, miR-150-5p act as a tumor suppressor in MLL-rearranged and other subtypes of acute myeloid leukemia (AML), by targeting HOXA9 and MEIS1, either directly or indirectly." (PMID 27447965, 2016). "We further confirmed that MEIS1 and HOXB7 or MEIS1 and HOXD8 combinations are genuinely synergistic in leukemia induction." (PMID 26606454, 2015). "SYC-522 significantly inhibited methylation at H3K79, but not H3K4 or H3K27, and decreased the expression of two important leukemia-relevant genes, HOXA9 and MEIS1, by more than 50%." (PMID 24858818, 2014). "EPZ004777 displayed selective killing of MLL-R leukemia cell lines and suppressed expression of the HOXA9 and MEIS1 oncogenes, consistent with the proposed role of the enzyme target." (PMID 23847761, 2013). "All mice that received Bcl-2+/+ cells transduced with HoxA9/Meis1 or MLL-AF9 developed rapid and aggressive leukemia with an average latency of 40 days." (PMID 24177192, 2013). "Excessive expression of FLT3 in MLL-rearranged leukemias results from direct transcriptional activation by HOXA9 and MEIS1 and post-transcriptional regulation by miR-150, a microRNA whose level is repressed by MLL fusion genes." (PMID 23977266, 2013). "This MLL-rearranged leukemia signature includes the HOXA cluster genes and the HOX cofactor MEIS1 gene which are direct transcriptional targets of MLL." (PMID 23977266, 2013). "Here we show increased expression of MEIS1, MEIS2, and PREP1 genes in leukemia-derived cell lines compared with blood normal cells." (PMID 22185299, 2011). "Besides, some of the DMRs with the strongest increases were adjacent to genes such as CEBPA, LEF1, PLK2, MEIS1 or TLE4, which have a known involvement in either leukemia or hematopoiesis." (PMID 38972954, 2024). "In preclinical models of KMT2A-r leukemia these molecules disrupt the menin-KMT2A interaction and inhibit the chromatin occupancy of menin and KMT2A at select KMT2A target genes leading to pronounced suppression of predominantly MEIS1, but also HOXA genes." (PMID 38174649, 2023). "The transcriptional expression of MEIS1 and HOX genes was crucial for the development of leukemia." (PMID 37049787, 2023).